RAG1 (recombination activating 1)
Diseases named in the same sentence as RAG1 in open-access papers (continued):
Sharing a sentence is not in itself a finding about the gene and the disease.
severe combined immunodeficiency (continued). "Other studies have reported CID with CD4 lymphopenia in patients bearing hypomorphic mutations in genes which are typically associated with severe combined immunodeficiency (SCID) phenotype, such as RAG1, which is known to cause SCID when mutated in amorphic manner." (PMID 25205547, 2014). "Defects in RAG1 and RAG2 are known to cause a T-B-NK+ form of severe combined immunodeficiency." (PMID 26186701, 2015). "Severe defects of V(D)J recombination, such as complete RAG1 or RAG2 deficiency, prevent proper rearrangement and recombination of the TCR and BCR genes and thus result in severe combined immunodeficiency (SCID), which impacts both T and B cell lineages." (PMID 41607487, 2025). "Genetic defects that abrogate RAG1 or RAG2 function lead to the T- B- severe combined immunodeficiency (SCID), a life-threatening disorder of the adaptive immune system." (PMID 38022635, 2023). "The most extreme syndrome of lymphocyte dysfunction, severe combined immunodeficiency (SCID), arises from mutations in a number of genes: IL2RG, RAG1, RAG2, ADA, JAK3, and IL7RG." (PMID 36839582, 2023). "Genetic defects in the recombination activating genes, RAG1 and RAG2 are known to impair V(D)J recombination in developing B and T-cells, thereby causing T-B-severe combined immunodeficiency (SCID)." (PMID 24678313, 2014). "The first reported case involved the RAG1 gene (Recombination Activating Gene-1) in a patient with Omenn's syndrome, a primary immunodeficiency, and the second the CD3ζ gene in a patient with severe combined immunodeficiency (SCID)." (PMID 18941616, 2008). "Mutations that inactivate RAG1 or RAG2 function in humans or knockout mice prevent antigen receptor rearrangement and block T and B lymphocyte development, leading to severe combined immunodeficiency (SCID)." (PMID 38467629, 2024). "Inactivation of RAG1 or RAG2 leads to severe combined immunodeficiency (SCID)." (PMID 36311661, 2022). "During V(D)J recombination, DNA double-strand breaks (DSBs) near the V, D, and J coding gene segments and recombination signal sequences are introduced by the recombination activating gene (RAG1 and RAG2) complex, and mutations in these two genes can lead to severe combined immunodeficiency (SCID)." (PMID 34825286, 2022). "The classical example is severe combined immunodeficiency (SCID) with defects in T cells, B cells, and NK cells caused by defects in IL2RG, RAG1/2, ADA, JAK3, and IL7R genes, in which an increased risk of disseminated VZV infection has been well-recognized for many years." (PMID 32495195, 2020). "Knockdown of RAG1 or RAG2 in mice results in lymphopenia and, therefore, severe combined immunodeficiency (SCID)." (PMID 35583713, 2022). "Mutations in genes that affect the development or function of T and B cells [DCLRE1C(ARTEMIS), ZAP70, RAG1/2, IL2RG, ILRA7, LIG4, JAK3, ADA] can result in intestinal inflammation along with recurrent infections from severe combined immunodeficiency (SCID)." (PMID 34122435, 2021). "RAG1/2,DCLRE1C,PRKDC,NHEJ1, andLIG4 result in isolated non-syndromic combined immunodeficiency (CID, due to low-T low-B CID) while defects in other genes cause syndromic combined immunodeficiencies (due to the additional roles of these genes in non-immune cells)." (PMID 35713311, 2022).
Omenn syndrome (30 papers, 2008 to 2026). An inflammatory condition characterized by erythroderma, desquamation, alopecia, chronic diarrhea, failure to thrive, lymphadenopathy, and hepatosplenomegaly, associated with severe combined immunodeficiency (SCID). "The diagnosis of SCID with Omenn syndrome was made, with genetic analysis revealing compound heterozygosity for pathogenic RAG1 variants." (PMID 41727494, 2026). "For comparison, a known pathogenic RAG1 L526R variant from a patient with Omenn syndrome was included together with the RAG1 WT control to help illustrate the degree of recombination defect in the family reported here." (PMID 39812873, 2025). "Early HSCT rescued our patient with a RAG1 mutation (P365) and stopped the development of an autoimmune disorder (Omenn syndrome)." (PMID 32670274, 2020). "Missense mutations in either RAG-1 or RAG-2 genes are also observed in humans with an analogous form of autosomal recessive SCID known as Omenn syndrome." (PMID 29181194, 2017). "Genetic studies of polymorphisms in wild-type and Omenn syndrome patients as well as biochemical data characterising recombinatorial competence of Omenn syndrome mutants suggest that RAG-1 and RAG-2 mutants exhibit lower efficiency of V(D)J recombination." (PMID 29181194, 2017). "In this report, we describe an infant with Omenn syndrome with a previously unreported termination mutation (p.R142*) in Rag1 on one allele and a partially characterized substitution mutation (p.V779M) in a “core” region of the other Rag1 allele." (PMID 25849362, 2015). "We present here an infant boy with Omenn Syndrome bearing compound heterozygous mutations of Rag1: a nonsense mutation on the maternal allele (p.R142*) and a missense mutation on the paternal allele (p.V779M)." (PMID 25849362, 2015). "Omenn Syndrome can be caused by mutations in Rag1 and Rag2, or rarely by mutations in the NHEJ factor Artemis, in the IL-7 receptor alpha chain or in the RNase mitochondrial RNA processing (RMRP) gene." (PMID 25849362, 2015). "The majority of mutations in Omenn syndrome are missense mutations in recombinase activating genes RAG1 and RAG2." (PMID 25161792, 2014). "For instance, null mutations of RAG1 are known to cause SCID while hypomorphic mutations have been associated with Omenn syndrome or idiopathic CD4 lymphopenia." (PMID 25205547, 2014). "This is the first report in the literature linking a homozygous R396H mutation in the RAG1 gene with presentation of Omenn's syndrome." (PMID 19830075, 2009). "Future studies will test the hypothesis that hypofunctional Rag1 and Rag2 mutants can confer susceptibility to Omenn Syndrome by impairing the post-cleavage stage of V(D)J recombination." (PMID 25849362, 2015). "Indeed, more than 90% of Omenn Syndrome cases are attributable to hypomorphic mutations in Rag1 and Rag2." (PMID 25849362, 2015). "Furthermore, spontaneously increased serum IgE levels are detected in MHC-II-deficient and T-lymphopenic mice or in Omenn syndrome patients with reduced Rag1 or Rag2 activity." (PMID 26523376, 2015). "In addition to causing the SCID phenotype, hypomorphic mutations in RAG1 or RAG2 can lead to partially impaired V(D)J recombinational activity resulting in Omenn syndrome (OS)." (PMID 19912631, 2009). "However, biochemical assays demonstrate that the paternal missense mutation does not affect catalysis of V(D)J cleavage in vitro, supporting that hypomorphic Rag1 activity in the post-cleavage stages of recombination is sufficient to confer susceptibility to Omenn Syndrome." (PMID 25849362, 2015). "One specific example where we improve the prediction of gene–disease associations is for the disease Omenn syndrome (OMIM:603554) which is associated with three genes: DCLRE1C (ENTREZ:64421), RAG2 (ENTREZ:5897) and RAG1 (ENTREZ:5896)." (PMID 37550716, 2023).
Omenn syndrome (continued). "These activated T-cells can be of maternal origin in SCID with maternal engraftment (JAK3 with maternal engraftment) or can be oligoclonal, expanded T-cells in Omenn syndrome patients (RAG1 Omenn syndrome)." (PMID 32265901, 2020). "Our patients with IL2RG, RAG1/2, and AICDA mutations had Treg cell dysfunction causing lymphadenopathy and erythroderma (or severe atopic dermatitis) similar to Omenn syndrome, which is consistent with previous studies." (PMID 32670274, 2020). "Omenn syndrome (OS) shares the genetic aetiology of T-B-NK+ SCID, with mutations in RAG1, RAG2, or DCLRE1C." (PMID 19912631, 2009). "However, it negatively impacts patients with somatic variants in CARD11, RAG1, as well as in a reported case of IL2RG reversion in tissue infiltrating T-cells, all associated with Omenn syndrome." (PMID 40711587, 2025). "In total, nearly half of the patients in the NBS group developed Omenn syndrome (all had mutations in RAG1), whereas there were no such cases in the clinical group (43% vs 0%, P = 0.03)." (PMID 38165471, 2024). "Multiple genes presenting as Omenn syndrome, such as RAG1/2, ADA, LIG4, ZAP70, etc." (PMID 37755421, 2023). "In T-B-NK + SCID/Omenn syndrome phenotype without microcephaly, variants in RAG1/2 were detected in 41 patients from 38 different families." (PMID 35482138, 2022). "SCID patients had disease-causing mutations in RAG1 or RAG2 (n = 4, two of them presented with Omenn syndrome), IL2RG (n = 4, one of them with confirmed maternal engraftment), NHEJ1 (n = 1), CD3E (n = 1), ADA (n = 1), JAK3 (n = 3, two of them with maternal engraftment) and DCLRE1C (n = 1)." (PMID 32265901, 2020). "After clinical efficacy and safety has been demonstrated in this patient group, wider implementation could be considered, potentially not only for RAG1-SCID, but also for Omenn syndrome and other RAG1 deficiencies." (PMID 32322605, 2020). "In the RAG1-86nt hamster reported herein, we genetically disrupted the N-term non-core domain of RAG1 of the Syrian hamster to represent another subset of genetic causes for Omenn Syndrome." (PMID 29734775, 2018). "For example, about 19% of the genetic mutations in the RAG1 gene that cause Omenn syndrome occur in the sequences of the RAG1 gene encoding the non-core domain of RAG1." (PMID 29734775, 2018). "Here, we report the production and characterization of the RAG1-86nt Syrian hamster carrying a reading frameshift deletion disrupting the N-terminal non-core domain of RAG1 to recapitulate a subtype of the genetic mutations of Omenn syndrome." (PMID 29734775, 2018). "A similar frame shift mutations like in the LEW/Ztm-Rag1em1Ztm were observed in the human Rag1 gene in two patients with Omenn’s syndrome carrying an adenosine deletion at position 877 of the Rag1 cDNA also introducing a premature stop codon in front of the nonamer binding region (NBR)." (PMID 23136839, 2012). "For example, in T-B-NK + SCID/Omenn syndrome phenotype without microcephaly (n = 47), Sanger sequencing of RAG1/2 genes identified the pathogenic variants in 39 patients (82.9%), thus limiting the need for NGS to almost less than one-fifth of the patients with these phenotypes." (PMID 35482138, 2022). "However, others have argued that by using this approach, it is not possible to fully correct the RAG1 immune deficiency, and that oligoclonal T cells could develop, reminiscent of human Omenn syndrome, a disorder known to arise from hypomorphic RAG mutations, resulting in low recombinase activity." (PMID 32322605, 2020).
leukemia (24 papers, 2012 to 2025). A malignant (clonal) hematologic disorder, involving hematopoietic stem cells and characterized by the presence of primitive or atypical myeloid or lymphoid cells in the bone marrow and the blood. "Given that C>T mutations also arise by spontaneous deamination of methylated cytosine, leading to COSMIC SBS1 we compared the 5'-NCG-3' trinucleotide context for C>T mutations in the RAG-1 KO leukemia to SBS1." (PMID 41158994, 2025). "We therefore assume that spontaneous development of leukemia in RAG1-deficient mice is also likely in other breeding colonies." (PMID 35583713, 2022). "We conclude that facilities that breed RAG1-deficient mice should be aware of the risk of leukemia development in this strain and recommend to implement regular blood sampling for aged RAG1-deficient animals." (PMID 35583713, 2022). "Aberrant Rag1/2 activity is linked to oncogenic translocations associated with immature human and mouse B and T leukemia/lymphoma." (PMID 34322489, 2021). "Consistent with the causal relationship between RAG1/2 activity and cancer progression, deficiency of RAG1/2 prevents leukemia development in mouse models." (PMID 32411637, 2020). "Leukemias and lymphomas have specific somatic deletions and chromosomal translocations that exhibit signatures of RAG1/2 activity and related mutational processes." (PMID 32411637, 2020). "To demonstrate the efficacy of ruxolitinib in leukemia driven by an IL7Rα mutation, we performed therapeutic studies in Rag1−/− mice engrafted with D1_hIL7RP1." (PMID 29854301, 2018). "In summary, we propose Aid as a negative regulator in Rag1 deficient pro-B cells, whereby Aid clears aberrant pro-B cells that are leukemia prone." (PMID 29100269, 2017). "Since the reduction and loss of Aid expression at the Rag1 deficient pro-B cell stage accelerated the leukemia incidence, we suggest Aid expression as a negative regulator in Rag1 deficient pro-B cells to clear pre-leukemic populations." (PMID 29100269, 2017). "We examined the WES data to identify acquired mutations in ATC-treated RAG-1 KO leukemia samples." (PMID 41158994, 2025). "As the Scid mutation results in impaired T cell development, we examined whether T lymphopenia caused by RAG1 deficiency can also promote spontaneous leukemia development." (PMID 36765626, 2023). "Furthermore, experimental data obtained from RAG1-deficient mice might be affected by undetected development of leukemia." (PMID 35583713, 2022). "GSEA comparing RAG-1 KO BCP-ALL to murine BCP-ALL (GSE221597) revealed enrichment of genes expressed in ATC-induced leukemias." (PMID 41158994, 2025). "This single base substitutions (SBS) signature was highly reproducible across all RAG-1 KO leukemia samples, including 7 BCP-ALL and 1 pre–T-LBL (8660_Thymus), with a consistent preference for the following order: CCG > GCG > ACG > TCG." (PMID 41158994, 2025). "High incidence of recombination events, RAG recombinase aberrant activity and high RAG1 gene expression have been repeatedly reported in ETV6-RUNX1 leukemia or equivalent mouse models." (PMID 34535762, 2022). "We thereby present a novel mechanism of Notch1-mediated transcriptional activation of Rag1 and Rag2, involved in both T-cell development and leukemia." (PMID 34322489, 2021). "As there are no definitive genetic markers to identify this novel subtype, the RAG1‐signature represents a means to screen for this leukemia in children." (PMID 33987955, 2021). "We also noted strong inverse correlations between RUNX1 and RAG1/RAG2 mRNA expression in a panel of human leukemias and lymphomas." (PMID 27056890, 2016). "We found that high expression of RAG1/2 or AICDA is markedly distinct between different subtypes of pre-B-ALL at the leukemia state." (PMID 27431763, 2016).
leukemia (continued). "We first selected five hematopoietic leukemia cell lines for which RAG1/2 activity has been previously quantified using a classical episomal substrate and readout of recombination by differential antibiotic resistance of subsequently transfected bacteria." (PMID 23720659, 2013). "Furthermore, expression of catalytically inactive RAG1 has been shown to accelerate progression of chronic lymphocytic leukemia in a leukemia-prone mouse line." (PMID 35583713, 2022). "Hence, the leukemia arose from pro-B cells, which were unable to undergo Rag1-mediated V(D)J-recombination." (PMID 29100269, 2017). "In addition, it has been shown that SV in this type of leukemia have a signature of immunoglobulin recombination activating genes (RAG1/2)-mediated rearrangements while the SNVs have an APOBEC signature." (PMID 29178827, 2017). "Mice overexpressing PRDM14 in HSCs typically succumb to leukemia by 8-weeks of age, precluding our ability to make this observation previously and making the Rag1−/− genetic background ideal for future studies to fully dissect the function of PRDM14 in hematopoietic progenitor cells." (PMID 27106930, 2016). "To detect early leukemia development in the remaining animals of generation x + 1 before onset of leukemia-associated symptoms, we then started to perform monthly screenings for elevated CD19+ blast populations in the peripheral blood of all RAG1-deficient animals in our colony." (PMID 35583713, 2022). "Similarly, the over ten-fold higher RAG1 expression could also be relevant for the prevalent development of leukemia carrying the ETV6-RUNX1 initiating fusion." (PMID 27431763, 2016). "In this study, we have demonstrated that non-core region deletion of both Rag1 and Rag2 leads to accelerated development of leukemia and increased off-target V(D)J recombination in mouse models of BCR-ABL1+ B cells." (PMID 39056282, 2024). "Rag1-deficient hosts enabled CAR T cell expansion without irradiation and limited CAR T cell antigen exposure to CD19 densities expressed on leukemia rather than endogenous B cells." (PMID 38196657, 2023). "As R26PR;MMTV-cre;Rag1−/− mice did not develop leukemia, we determined hematopoietic phenotypes by performing flow cytometry for stem and progenitor cells in the bone marrow." (PMID 27106930, 2016). "Gene expression analyses indicated that both the rag2:Myc and rag2:Myc + rag2:prl-3 leukemias expressed the lymphocyte specific genes rag1 and rag2 and the T-cell genes lck and tcrB, but not B-cell related genes igD or igM, indicating all leukemias generated were of T-cell origin." (PMID 32001668, 2020). "Defining the RE by simple percentage analysis for each cell type allowed their ranking for RAG activity, in concordance with that established earlier, although we did not detect the residual RAG1/2 activity reported to occur in the leukemias of myeloid lineage HL-60 and K-562." (PMID 23720659, 2013). "The non-core domain deletion in both Rag1 and RAG2 led to accelerated leukemia onset and progression, as well as an increased off-target V(D)J recombination." (PMID 39056282, 2024). "Molecular profiling of isolated leukemia cells confirmed expression of lymphoid (rag1 and rag2) and T-cell specific (lck and tcrβ-C2) markers, with no significant upregulation of B-cell genes (pax5, igD-VH1, and igM-VH1), indicating that PRL-3 did not alter leukemia lineage identity." (PMID 40463094, 2025).